CDK5R2 (cyclin dependent kinase 5 regulatory subunit 2)
Description:
Activator of CDK5/TPKII.
Synonyms: NCK5AI; p39nck5ai; P39
Tractability: Antibody: UniProt places it where antibodies can reach, with high confidence; its Gene Ontology location is reachable by antibodies, with medium confidence.
Gene: Protein-coding gene on chromosome 2 (218,959,666 to 218,962,155, forward strand). Ensembl gene ENSG00000171450.
Subcellular location: Cell membrane
Pathways (Reactome):
Signal Transduction: NGF-stimulated transcription
Gene Ontology:
Molecular function: actin binding; cyclin-dependent protein serine/threonine kinase activator activity; protein kinase binding
Biological process: axon guidance; brain development; regulation of cyclin-dependent protein serine/threonine kinase activity; regulation of cytoskeleton organization
Cellular component: plasma membrane; cytoplasm; growth cone; membrane; neuron projection; presynapse; protein kinase 5 complex
Genetic constraint (gnomAD): Loss-of-function variants: 7 observed, 17.64 expected, observed/expected ratio (o/e) 0.4, 90% interval 0.22 to 0.75. The upper end of that interval is the gene's LOEUF score, 0.75, which puts it in group 3 of 6, group 1 being the genes least tolerant of losing a copy. Missense variants: 368 observed, 427.79 expected, observed/expected ratio (o/e) 0.86, 90% interval 0.79 to 0.94. Synonymous variants: 234 observed, 213.31 expected, observed/expected ratio (o/e) 1.1, 90% interval 0.99 to 1.22.
Homologues: Orthologues: chimpanzee CDK5R2 (99% identical), macaque CDK5R2 (99% identical), mouse Cdk5r2 (96% identical), pig CDK5R2 (91% identical), rat Cdk5r2 (91% identical), tropical clawed frog cdk5r2 (56% identical), zebrafish cdk5r2b (47% identical), Caenorhabditis elegans cdka-1 (32% identical), guinea pig Cdk5r2 (25% identical). Paralogues in human: CDK5R1 (47% identical).
Diseases named in the same sentence as CDK5R2 in open-access papers:
CDK5R2 is named in the same sentence as 8 diseases in open-access papers, as found by Europe PMC text mining. Sharing a sentence is not in itself a finding about the gene and the disease. The quoted sentences say what the papers report.
lung carcinoma (3 papers, 2018 to 2024). "These genes include GRIA3, TAF7L, ARL14, PCDHGA9, MDGA1, ZFPM2, OSR2, TMC8/TMC6, HCN2, and CDK5R2, which are likely to be relevant in human lung cancer and are also epigenetically deregulated upon exposure to ECS in our animal study." (PMID 39273313, 2024). "Moreover, CDK5R2/p39 increased the invasiveness of lung cancer by impairing cell adhesion and promoting epithelial-to-mesenchymal transition." (PMID 32444802, 2020).
hepatocellular carcinoma (1 paper, 2022). A malignant tumor that arises from hepatocytes. "In hepatocellular carcinoma, patients with a low expression of CDK5R2 in tumor displayed poor overall survival." (PMID 36713370, 2022).
lymph node metastasis (1 paper, 2022). "After taking the intersection with GSE101448, 13 genes (CDK5R2, SYT7, CACNA2D2, etc.)which might prevent lymph node metastasis were further selected." (PMID 36344976, 2022).
neuroblastoma (1 paper, 2024). Neuroblastoma (NB) is the most common solid, extracranial childhood tumor. "Studies have shown that CDK5R2 CYP26B1, DCAF8L1, PAGE1, and TRIM36 can be used to construct prognostic models or prognostic biomarker for HCC, rectal cancer, neuroblastoma, etc." (PMID 38649860, 2024).
cancer (3 papers, 2012 to 2024). A tumor composed of atypical neoplastic, often pleomorphic cells that invade other tissues. "Most HCC tissues exhibited elevated protein levels of CDK5R2, CYP26B1, DCAF8L1, PAGE1, and TRIM36 in comparison to para-carcinoma tissues, as indicated by the results." (PMID 38649860, 2024). "CDK5R2, NEK9, PRKCA, PXK and STK11 have significant effects on growth of cancer cells in all cancer cell lines." (PMID 22761558, 2012). "CCNB1IP1, CCNC, CCND2, CDK5R2, CDK9, and GAK were upregulated in all three cancer regions." (PMID 33302383, 2020).
tumor (2 papers, 2022 to 2024). "Recognizing the critical role of m1A in tumor progression and prognosis, a reliable prognostic signature based on five DEGs characterizing autophagy among the m1A modification patterns (CDK5R2, CYP26B1, DCAF8L1, PAGE1, and TRIM36) was initially established." (PMID 38649860, 2024). "This analysis identified TRIM36, CYP26B1, PAGE1, CDK5R2, and DCAF8L1 as a molecular signature associated with tumor aggressiveness." (PMID 38649860, 2024).
CDK5R2 also shares sentences with these, for which no sentence is quoted: benign neoplasm (1 paper); rectal cancer (1).